TRPC1 (transient receptor potential cation channel subfamily C member 1)
Diseases named in the same sentence as TRPC1 in open-access papers (continued):
Sharing a sentence is not in itself a finding about the gene and the disease.
synovial sarcoma (3 papers, 2018 to 2024). "In human SW982 synovial sarcoma cells (SSCs), EA induces TRPC1/C4 heterodimer activation and cell cytotoxicity, which is inhibited by Pico145, an inhibitor of the TRPC1/C4 channels." (PMID 31801263, 2019). "In synovial sarcoma cells, TRPC1 depletion induced a double-rectifying I-V curve." (PMID 39397856, 2024). "Interestingly, TRPC1 depletion induced double-rectifying I–V curves in synovial sarcoma cells." (PMID 39397856, 2024). "Our recent study has demonstrated that the activation of heteromeric TRPC4 and TRPC1 (TRPC4/C1) causes a potent cytotoxic effect on SW982 cells mediated via Na+ loading, suggesting that heteromeric TRPC4/C1 is a promising target of anti-tumor agents against synovial sarcoma." (PMID 29757938, 2018).
Allergy (2 papers, 2025). An allergy is an immune response or reaction to substances that are usually not harmful. "Another finding that expands the understanding of the molecular basis of HDM allergy is the role of TRPC1 (transient receptor potential canonical 1) channel." (PMID 40565123, 2025).
Alzheimer disease (2 papers, 2020 to 2024). A progressive, neurodegenerative disease characterized by loss of function and death of nerve cells in several areas of the brain leading to loss of cognitive function such as memory and language. "Likewise, TRPC1 has been found to be neuroprotective in animal models of Parkinson’s disease and Alzheimer’s disease." (PMID 33490083, 2020).
breast tumor (2 papers, 2020 to 2021). "The higher TRPC1 expression found in small histological grade 1 breast tumors, relative to larger grade 3 tumors, is related to their greater propensity to undertake EMT." (PMID 35141145, 2021).
diabetic retinopathy (2 papers, 2020 to 2024). "TRPC1/4/5/6 are expressed in endothelial and Müller cells, and TRPC1/4/5/6(−/−) compound knockout mice showed resistance to diabetic retinopathy." (PMID 38732096, 2024).
Duchenne muscular dystrophy (2 papers, 2019 to 2021). Duchenne muscular dystrophy (DMD) is a neuromuscular disease characterized by rapidly progressive muscle weakness and wasting due to degeneration of skeletal, smooth and cardiac muscle. "TRPC1 and caveolin-3 protein levels have been shown to increase in the skeletal muscle from mice with Duchenne muscular dystrophy, and TRPC1 is activated by ROS in an Src kinase-dependent manner." (PMID 34174803, 2021). "Consistent with the accumulated data from the mdx mouse model, human myoblasts isolated from Duchenne muscular dystrophy (DMD) patients showed a significant increase in SOCE but no increase in levels of TRPC1, Stim1 or Orai1." (PMID 30298191, 2019).
endothelial dysfunction (2 papers, 2019 to 2026). In vascular diseases, endothelial dysfunction is a systemic pathological state of the endothelium (the inner lining of blood vessels) and can be broadly defined as an imbalance between vasodilating and vasoconstricting substances produced by (or acting on) the endothelium. "We hypothesize that TRPC1, TRPC3, TRPC4, and TRPC6 act as critical molecular effectors mediating hypoxia-driven calcium influx and downstream signaling pathways that lead to pulmonary vascular remodeling, endothelial dysfunction, and increased pulmonary arterial pressure." (PMID 41751997, 2026).
esophageal cancer (2 papers, 2022 to 2024). A primary or metastatic malignant neoplasm involving the esophagus. "In summary, SKF96365 induces apoptosis (PARP, caspase-9, and BCL-2) and autophagy (LC3-A/B) by inhibiting TRPC1 in esophageal cancer cells, thereby inhibiting tumor growth." (PMID 39165489, 2024). "In conclusion, our results demonstrate that SKF96365 inhibits tumor growth by inhibiting TRPC1 in esophageal cancer cells and inducing apoptosis (PARP, caspase-9, and BCL-2) and autophagy (LC3-A/B)." (PMID 39165489, 2024). "Therefore, we believe that SKF96365 plays an antitumor role in esophageal cancer by disturbing the expression of TRPC1." (PMID 39165489, 2024). "In esophageal carcinoma, silencing TRPC1 could repress cell viability and metastasis, indicating that TRPC1 is a protective factor in esophageal cancer." (PMID 35140788, 2022).
gastric tumor (2 papers, 2022 to 2024). "Forth, co-stimulation of NCX1 and TRPC1 with CaCl2 and Hp virulence factors promoted GC cell proliferation, migration and invasion in vitro, and increased gastric tumor size, number and peritoneal dissemination in vivo." (PMID 35882979, 2022).
Hypoglycemia (2 papers, 2024). A decreased concentration of glucose in the blood. "Collectively, these results show that Trpc1/4/5/6–/– mice develop an aggravated insulin-induced hypoglycemia which is associated with reduced plasma adrenaline levels." (PMID 39375537, 2024). "Indeed, compared with the wild-type mice, the TRPC1/4/5/6-deficient mice exhibited aggravated hypoglycemia at any time point analyzed until 60 min after the insulin administration." (PMID 39375537, 2024). "On the contrary, the rise in plasma adrenaline levels that was evoked by hypoglycemia was blunted by TRPC1/4/5/6 deletion." (PMID 39375537, 2024). "We show that insulin-evoked hypoglycemia is severely aggravated in mice lacking the cation channel proteins TRPC1, TRPC4, TRPC5, and TRPC6, which cannot be explained by alterations in glucagon or glucocorticoid action." (PMID 39375537, 2024).
ischemia (2 papers, 2021 to 2024). A hypoperfusion of the BLOOD through an organ or tissue caused by a PATHOLOGIC CONSTRICTION or obstruction of its BLOOD VESSELS, or an absence of BLOOD CIRCULATION. "BRL, in addition to iloprost which is routinely being used clinically and treatment modalities that includes BRL, TRPA1, and TRPC1 need to be investigated in detail for the effects on the ischemia originated diseases." (PMID 34174803, 2021).
liver cancer (2 papers, 2018 to 2021). An epithelial or non-epithelial malignant neoplasm that arises from the liver. "In the liver cancer cells Huh7, Ca2+ entry into the cells was found to significantly increase and cell proliferation slowed after TRPC1 silencing, which may be related to changes in MAPK signaling pathways." (PMID 33854967, 2021).
metastatic tumors (2 papers, 2021). "Further analysis of TRPC1 levels in primary and metastatic tumors of human CRC tissue microarray demonstrated that the TRPC1 protein expression was markedly enhanced in human metastatic CRC tissues." (PMID 34642309, 2021). "Our data indicated that gene expression of ZEB1, a major transcription factor in EMT, can predict TRPC1 mRNA expression, both in primary and metastatic tumors." (PMID 34936030, 2021). "Additionally, TRPC1 expression is significantly increased in metastatic tumor biopsies compared to primary biopsies." (PMID 34936030, 2021).
retinal degeneration (2 papers, 2011 to 2024). Degeneration of the retina. "For this purpose, we have considered the possibility that the TRPC1 and TRPC5 channels are involved in the maintenance of retinal calcium homeostasis, forming the heterodimer complex with special relevance during retinal degeneration due to RP." (PMID 39000357, 2024).
schizophrenia (2 papers, 2019 to 2022). A major psychotic disorder characterized by abnormalities in the perception or expression of reality. "Of these, Plscr4, Armc8, Zbtb38, Rbp1, Zic1, and Trpc1 have been linked to schizophrenia or schizophrenia-related disorders in previous studies." (PMID 31920576, 2019).
tauopathies (2 papers, 2020 to 2024). "Therefore, TRPC1 may serve as a promising therapeutic target for tauopathies." (PMID 32815315, 2020).
tongue squamous cell carcinoma (2 papers, 2024). A squamous cell carcinoma that arises from the tongue. "Compared with adjacent tissues, the expression of TRPC1 is increased in tongue squamous cell carcinoma tissues, thus having a clinical role in distinguishing and predicting tumor risk." (PMID 39759147, 2024). "Research indicates that TRPC1 knockdown inactivates the PI3K/AKT pathway, thereby reducing the proliferation and invasion of tongue squamous cell carcinoma cells." (PMID 39759147, 2024).
airway hyperresponsiveness (1 paper, 2024). "The activation of the TRPC1 channel on macrophages is beneficial for regulating the function of TRPC1 channel and adipocytes around adipose tissue, promoting the secretion of inflammatory factors by macrophages, which enter the lungs and cause airway hyperresponsiveness." (PMID 38365763, 2024).
Arrhythmia (1 paper, 2022). Any cardiac rhythm other than the normal sinus rhythm. "Another potential pathologic consequence of chronically increased SR leak through TRPC1 channels is increased susceptibility to arrhythmia." (PMID 36620209, 2022).
atrial fibrillation (1 paper, 2012). A disorder characterized by an electrocardiographic finding of a supraventricular arrhythmia characterized by the replacement of consistent P waves by rapid oscillations or fibrillatory waves that vary in size, shape and timing and are accompanied by an irregular ventricular response. "It was reported that mRNA and protein of TRPC1/3 channels were upregulated in human atrial tissue with atrial fibrillation and a goat model of atrial fibrillation." (PMID 22802050, 2012).
bladder overactivity (1 paper, 2013). "In conclusion, our data indicated that TRPC1 and TRPC4 are important players in the development of bladder dysfunction in the CYP-induced overactive bladder, by promoting bladder-afferent sprouting in mucosa." (PMID 23922735, 2013). "Our study highlights a crucial role of both TRPC1 and TRPC4 in bladder-afferent nerve sprouting and in bladder dysfunction in a chemically induced overactive bladder model." (PMID 23922735, 2013). "Here, we show increased expression of TRPC1 and TRPC4 in bladder-innervating sensory neurons, and provide evidence for their involvement in afferent sprouting and concomitant bladder overactivity in the chronic cyclophosphamide (CYP) model of cystitis." (PMID 23922735, 2013). "Collectively, our data suggest that TRPC1 and TRPC4 are involved in the sprouting of sensory neurons following bladder cystitis, which leads to overactive bladder disease." (PMID 23922735, 2013).
carcinosarcoma (1 paper, 2021). A malignant tumor composed of a mixture of carcinomatous and sarcomatous elements.
Cerebral ischemia (1 paper, 2020). Restriction of arterial blood supply to the brain associated with insufficient oxygenation to support the metabolic requirements of the tissue. "For TRPC1, both the MCAO model and OGD assay suggested that TRPC1 plays a protective role against neuronal injuries caused by cerebral ischemia/reperfusion through suppression of ROS generation." (PMID 33490083, 2020). "We provide our own data showing that TRPC1/C4/C5, especially TRPC4, may be generally detrimental in OGD and cerebral ischemia/reperfusion." (PMID 33490083, 2020).
cervical adenocarcinoma (1 paper, 2022). An adenocarcinoma arising from the cervical epithelium. "TRPC1 and TRPC6 mutations mainly occurred in cervical adenocarcinoma, while TRPC4, TRPV and TRPM were mainly mutated in cervical squamous cell carcinoma, which indicated that TRPs mutations could be one of the causes of cervical cancer." (PMID 36072430, 2022). "The expression levels of TRPV, TRPC and TRPM were decreased in cervical squamous cell carcinoma and cervical adenocarcinoma, with more obvious trend of TRPV1 and TRPC1, while the expression of TRPV and TRPM increased." (PMID 36072430, 2022).
chronic myeloid leukemia (1 paper, 2022). "TRPV2, TRPM7 and TRPC1 have been studied in chronic myeloid leukemia (CML) cell lines (K-562, KU812, MOLM-6 and 32D-p210)." (PMID 36330491, 2022).
chronic obstructive pulmonary disease (1 paper, 2017). A chronic and progressive lung disorder characterized by the loss of elasticity of the bronchial tree and the air sacs, destruction of the air sacs wall, thickening of the bronchial wall, and mucous accumulation in the bronchial tree. "We investigated the effects of TRPC1 on epithelial mesenchymal transition (EMT) in human airway in chronic obstructive pulmonary disease (COPD)." (PMID 29068985, 2017).
cognitive deficits (1 paper, 2020). "These in vivo data demonstrate that overexpression of TRPC1 induces synaptic impairments and cognitive deficits." (PMID 32815315, 2020). "Our results showed that overexpressing TRPC1 increased tau phosphorylation at these sites and elicited cognitive deficits, while pharmacological inhibiting or knockout TRPC1 attenuated these tau phosphorylation sites with improved synaptic and cognitive functions." (PMID 32815315, 2020).
colorectal tumor (1 paper, 2021). "TRPC1 knockdown inhibited cell proliferation, cell-cycle progression, invasion, and migration in vitro, as well as tumor growth in vivo; whereas TRPC1 overexpression promoted colorectal tumor growth and metastasis in vitro and in vivo." (PMID 34642309, 2021). "Consistently, the mRNA expression of TRPC1 in the metastasis tumor tissues was significantly higher than the primary colorectal tumor tissues, which indicated that TRPC1 upregulation was related to CRC deterioration." (PMID 34642309, 2021).
coronary artery disease (1 paper, 2017). "Upregulation of TRPC1 expression in neointimal SMCs is critical for occlusive coronary artery disease progression in the pig model of neointimal hyperplasia after vascular injury via balloon angioplasty." (PMID 28756533, 2017).
coronary atherosclerosis (1 paper, 2017). Atherosclerosis of the coronary vasculature. "Thus, our data underscore the importance of macrophage TRPC1 expression in coronary atherosclerosis in MetS." (PMID 28756533, 2017). "However, the mechanism of how macrophage TRPC1 expression promotes coronary atherosclerosis progression remains unclear." (PMID 28756533, 2017).
cystitis (1 paper, 2013). Inflammation of the urinary bladder. "Taken together, these results indicate that the CYP-induced cystitis in rats induces the de novo expression of TRPC1 and TRPC4 in bladder sensory neurons." (PMID 23922735, 2013). "To assess a possible involvement of TRPC1 and/or TRPC4 in the process of neurite sprouting in cystitis, we compared changes in CYP-treated wild type mice and mice deficient in TRPC1, TRPC4 and TRPC1/C4 (Trpc1−/−, Trpc4−/− and Trpc1/c4−/− mice)." (PMID 23922735, 2013). "Further studies will be necessary to understand the underlying mechanisms by which TRPC1 and TRPC4 promote de novo nerve growth in murine cystitis." (PMID 23922735, 2013).
dopaminergic neuroblastoma (1 paper, 2012). A neuroblastoma associated with increased dopamine excretion. "Interestingly, a recent study reported that MPTP treatment induced ER stress and decreased AKT phosphorylation via loss of TRPC1-dependent ER Ca2+ homeostasis in human dopaminergic neuroblastoma SH-SY5Y cells." (PMID 22973882, 2012).
endometrioid tumor (1 paper, 2021). A benign, borderline, or malignant epithelial tumor of the female reproductive system characterized by the presence of glands and/or cysts lined by neoplastic cells that resemble endometrial cells. "In primary biopsies, TRPC1 expression correlates with high tumor grade, and is significantly higher in serous and carcinosarcoma tumors compared to endometrioid tumors." (PMID 34936030, 2021).
follicular thyroid cancer (1 paper, 2022). "The knockdown of the calcium signalling proteins TRPC1, STIM1 and ORAI, increased the expression of TRβ1, but decreased that of Runx2 in human follicular thyroid cancer ML-1 cells." (PMID 36497320, 2022).
fragile X syndrome (1 paper, 2025). A genetic syndrome caused by mutations in the FMR1 gene which is responsible for the expression of the fragile X mental retardation 1 protein. "Using a Cre-tamoxifen system, we acutely deleted Trpc1 in a Fragile X syndrome (FXS) mouse model, characterized by mGluR5 hyperactivity, enhanced mGluR-LTD, and social deficits." (PMID 40777047, 2025).
Hypercalcemia (1 paper, 2020). An abnormally increased calcium concentration in the blood. "Here, we show that mice lacking the transient receptor potential canonical channel 1 (TRPC1) develop chronic hypercalcemia, hypocalciuria, and elevated PTH levels, mimicking human FHH." (PMID 32213715, 2020). "Trpc1+/- male mice exhibited significant hypercalcemia, suggesting that heterozygous deletion of Trpc1 was sufficient to produce a hypercalcemic phenotype." (PMID 32213715, 2020). "Despite hypercalcemia, 24-hour urine Ca2+ excretion, renal Ca2+ clearance, and the urine Ca2+/creatinine ratio were all reduced in 7-month-old Trpc1–/– males and females." (PMID 32213715, 2020). "Hypercalcemia was present in either fasted in Trpc1–/– mutant male or female mice (10 hours prior to blood collection) or animals allowed to feed ad libitum, arguing against increased gut Ca2+ absorption as the mechanism for the hypercalcemia in mice lacking Trpc1." (PMID 32213715, 2020). "The phenotype of the Trpc1–/– mice is consistent with that of FHH in humans, and the possibility that mutations in the TRPC1 gene may be a cause of hypercalcemia in some patients with FHH who did not have CASR, GNA11, or AP2S1 mutations was therefore explored." (PMID 32213715, 2020). "Statistically, as a group, patients with FHH exhibit mild but significant hypercalcemia, while a few of them show elevated PTH, similar to male Trpc1–/– mice." (PMID 32213715, 2020). "Creatinine clearance in Trpc1–/– mice was comparable to that in WT mice, indicating that renal failure could not have accounted for the hypercalcemia and elevated PTH levels seen in Trpc1–/– mice." (PMID 32213715, 2020).
hyperthyroidism (1 paper, 2021). Overactivity of the thyroid gland resulting in overproduction of thyroid hormone and increased metabolic rate. "This suggests that capillary basal membrane thickening caused by increased ER stress in renal tissue due to hyperthyroidism is due to increased expression of TRPC1." (PMID 33754657, 2021). "It was determined that hyperthyroidism caused increment of TRPC1 expression that induces ER stress." (PMID 33754657, 2021). "As a result of our literature review, the effect of hyperthyroidism on the relationship between ER stress and TRPC1 channel in renal tissue was first demonstrated in this study." (PMID 33754657, 2021). "In light of all this information, we aimed to investigate the relationship between the pathways of TRPC1 signal transduction and ER-stress in kidneys, which are affected generally in hyperthyroidism." (PMID 33754657, 2021). "In this study, we suggested for the first time how the renal tissue is affected in hyperthyroidism in terms of the roles of ER stress and TRPC1 channel in this process." (PMID 33754657, 2021). "Hyperthyroidism caused an increase in expression of GRP78 (2.16 fold), ATF6 (2.82 fold), PERK (1.95 fold), IRE1 (1.60 fold), and TRPC1 (1.53 fold) when compared to the control group." (PMID 33754657, 2021).
Infertility (1 paper, 2025). "The expression of key circRNAs (hsa-SAP130_0002, hsa-TRPC1_0001, hsa-FBRS_0001, hsa-ACACA_0025, hsa-UTRN_0042, and hsa-ZNF532_0023) was then validated by qPCR, and their diagnostic accuracy for infertility was confirmed through receiver operating characteristic curve analysis." (PMID 40391511, 2025).
injury (1 paper, 2023). Damage inflicted on the body as the direct or indirect result of an external force, with or without disruption of structural continuity. "The pathogenesis of APAP-mediated acute liver injury involves the activation of TRPV1, TRPV4, TRPC1, TRPM2, and TRPM7 channels, which trigger the influx of Ca2+ into hepatocytes and subsequent cellular damage." (PMID 37569884, 2023).